LIPI (lipase I)
Description:
Hydrolyzes specifically phosphatidic acid (PA) to produce 2-acyl lysophosphatidic acid (LPA; a potent bioactive lipid mediator) and fatty acid. Does not hydrolyze other phospholipids, like phosphatidylserine (PS), phosphatidylcholine (PC) and phosphatidylethanolamine (PE) or triacylglycerol (TG).
Synonyms: CT17; mPA-PLA1 beta; LPDL; PRED5; mPA-PLA1beta; PLA1C
Tractability: Antibody: UniProt places it where antibodies can reach, with high confidence; its Gene Ontology location is reachable by antibodies, with high confidence; UniProt predicts a signal peptide or a membrane-spanning region; the Human Protein Atlas places it where antibodies can reach.
Gene: Protein-coding gene on chromosome 21 (14,108,813 to 14,210,955, reverse strand). Ensembl gene ENSG00000188992.
Subcellular location: Cell membrane (Isoform 1); Secreted; Cell membrane (Isoform 2)
Subcellular location (Human Protein Atlas): Plasma membrane; Predicted to be secreted
Pathways (Reactome):
Metabolism: Synthesis of PA
Gene Ontology:
Molecular function: heparin binding; phospholipase activity; carboxylic ester hydrolase activity; lipase activity
Biological process: lipid catabolic process; phosphatidic acid biosynthetic process; lipid metabolic process
Cellular component: extracellular region; plasma membrane
Genetic constraint (gnomAD): Loss-of-function variants: 17 observed, 12.43 expected, observed/expected ratio (o/e) 1.37, 90% interval 0.93 to 1.88. The upper end of that interval is the gene's LOEUF score, 1.88, which puts it in group 6 of 6, group 1 being the genes least tolerant of losing a copy. Missense variants: 227 observed, 214.42 expected, observed/expected ratio (o/e) 1.06, 90% interval 0.95 to 1.18. Synonymous variants: 85 observed, 73.79 expected, observed/expected ratio (o/e) 1.15, 90% interval 0.97 to 1.38.
Homologues: Orthologues: chimpanzee LIPI (99% identical), macaque LIPI (89% identical), rabbit LIPI (79% identical), dog LIPI (75% identical), pig LIPI (72% identical), guinea pig LIPI (70% identical), mouse Lipi (67% identical), rat Lipi (64% identical), zebrafish lipib (36% identical), Drosophila melanogaster CG6847 (31% identical), Drosophila melanogaster CG13282 (25% identical), Drosophila melanogaster CG34447 (21% identical), and 23 more. Paralogues in human: LIPH (45% identical), PLA1A (30% identical), LIPG (29% identical), LIPC (29% identical), PNLIP (28% identical), PNLIPRP2 (28% identical), PNLIPRP3 (27% identical), PNLIPRP1 (27% identical), LPL (27% identical).
Diseases named in the same sentence as LIPI in open-access papers:
LIPI is named in the same sentence as 11 diseases in open-access papers, as found by Europe PMC text mining. Sharing a sentence is not in itself a finding about the gene and the disease. The quoted sentences say what the papers report.
listeriosis (4 papers, 2008 to 2021). A bacterial infection caused by Listeria monocytogenes. "Particularly, the llsX gene (encoding Listeriolysin, LLS, a hemolytic and cytotoxic factor) belonging to LIPI-3, has been greatly associated with a subset of lineage I in human listeriosis." (PMID 31159734, 2019). "We accept that not all cases of listeriosis are associated with LIPI-3+ lineage I strains and that a small number of lineage I LIPI-3− strains have also been linked to epidemic listeriosis." (PMID 18787690, 2008). "The results show that several isolates harbor LIPI-3 and LIPI-4 genes, which may be a possible transmission route for Listeria infections in consumers." (PMID 32351479, 2020). "In addition, the findings of virulence markers (inlC, inlJ, LIPI-3, LIPI-4, and ECIII) concerned with the pathogenesis of human listeriosis and antibiotics resistance of L. monocytogenes in this study implies a potential public health risk." (PMID 33560938, 2021).
acute pancreatitis (1 paper, 2022). An acute inflammatory process that leads to necrosis of the pancreatic parenchyma. "This demonstrates that ferroptosis is associated with severe acute pancreatitis-induced AKI, and lipase I (LIPI) could inhibit ferroptosis, and both reduce renal damage and improve renal function." (PMID 35860360, 2022).
cancer (3 papers, 2017 to 2024). A tumor composed of atypical neoplastic, often pleomorphic cells that invade other tissues. "Membrane-associated phospholipase A1 beta (LIPI) is a cancer/testis antigens (CTA) that is highly tumor specific, making it a potential target for immune-based therapies as well." (PMID 31275859, 2019). "In line with this, LIPI was identified as a cancer/testes antigen (CTA), i.e., a group of immunogenic proteins showing predominant expression in gametogenic tissues and cancer and considered as interesting targets for anti-cancer vaccines." (PMID 39125098, 2024).
infection (1 paper, 2021). The state of being infected such as from the introduction of a foreign agent such as serum, vaccine, antigenic substance or organism. "Therefore, infection-associated isolates harboring LIPI-4 are typically considered hypervirulent." (PMID 34746033, 2021).
LIPI also shares sentences with these, for which no sentence is quoted: hypertriglyceridemia (2 papers); tumor (2); age-related macular degeneration (1); babesiosis (1); Ewing sarcoma (1); infections of the central nervous system (1); Insulin resistance (1).